IDO1 (indoleamine 2,3-dioxygenase 1)
Diseases named in the same sentence as IDO1 in open-access papers (continued):
Sharing a sentence is not in itself a finding about the gene and the disease.
tumor (continued). "A recent study described dramatically suppressed tumor growth upon IDO1 knockdown by increasing the number of CD4+ and CD8+ T cells in murine GBM models." (PMID 32117235, 2020). "Epacadostat in comparison selectively targets and binds to IDO1, reducing the catabolization of tryptophan in the tumor microenvironment." (PMID 32469935, 2020). "The stimulation of IDO1 accelerates the degradation of Trp into KYNs such as Kyn, impacting Trp availability for immune cells, which can modulate anti-tumor immune responses." (PMID 32957545, 2020). "Their data showed that tumours with a high level of IDO1 expression were more likely accompanied by abundant CD8+ T cell infiltration." (PMID 32227579, 2020). "Co-expression of Lgr5 and Ido1 mRNA was barely detectable by ISH in Stat1flox/floxApcMin tumor cells, indicating that IDO1+ cells are Paneth cells." (PMID 32444775, 2020). "The pY-STAT1+ tumor cells appeared as cell clusters, which differed from the alternating arrangement of IDO1+ Paneth cells." (PMID 32444775, 2020). "In a combined treatment with a clinically approved agent against immunosuppression (IDO1), the Fe‐doped CuO NPs were tested in vivo, resulting in complete tumor remission in multiple syngeneic subcutaneous mouse models." (PMID 31755189, 2020). "Our previous studies demonstrated that shRNA against Ido1, Foxo3, Thbs1, and Clec4a2 can enhance the antitumor effect of Her2/neu DNA vaccine in the murine tumor model." (PMID 32933162, 2020). "Meanwhile, NLG919‐S‐S‐PPa heterodimer can be cleaved under endogenous GSH conditions to release NLG919 for inactivating IDO‐1 as well as the immunosuppressive Tregs in the tumor microenvironment." (PMID 32328426, 2020). "In particular, AhR activation promotes conversion of effector T lymphocytes into Tregs and upregulates IDO1 expression in DCs, further amplifying immunoregulatory effects and blocking anti-tumor immunity." (PMID 33584695, 2020). "Tumor endothelial cell expression of IDO1 was positively correlated with T-cell infiltration and IFNγ expression in the tumor." (PMID 32231867, 2020). "A correlation between IDO1 expression and FoxP3+ Treg lymphocytes density in the tumor microenvironment of PTCs was observed." (PMID 33986723, 2020). "Previous study found that inhibiting IDO1 can restore the activity of T cells and improve the ability to kill tumor cells." (PMID 33552086, 2020). "A pivotal role in creating a tumor-tolerant microenvironment is played by the expression of the immunoregulatory enzyme IDO1 either by the tumor cells or by the DCs that move to tumor-draining lymph nodes." (PMID 33986723, 2020). "In cancer, IDO1 expression/activity has been observed in tumor cells as well as in the tumor-surrounding stroma, which is composed of endothelial cells, immune cells, fibroblasts, and mesenchymal cells." (PMID 33072086, 2020). "Multivariate analysis displayed that changes of tumor IDO1 expression after neoadjuvant treatment and pathological N staging were independent prognostic factors for OS, and only pathological N staging was independent prognostic factors for PFS." (PMID 32733806, 2020). "Further prospective studies with large sample size are warranted to confirm the influence of neoadjuvant therapy on tumor IDO1 expression in ESCC." (PMID 32733806, 2020). "IDO1 can be constitutively expressed by tumor cells or by macrophages, MDSCs and DCs in the tumor or the lymph nodes but can also be induced by inflammatory cytokines, such as IFN-γ, potentially inducing resistance to immunotherapy." (PMID 32793228, 2020). "In our study, the changes of tumor IDO1 expression was positively correlated with the changes of CD8+ TILs density after NCT; while no such correlation was observed in the NCRT group." (PMID 32733806, 2020).
tumor (continued). "To determine the relative expression level of IDO1 in endothelial cells as compared to the rest of the tumor tissue, we employed mice expressing a fusion eGFP-L10a ribosomal protein under control of the VE-cadherin promoter (VEcadTRAP mice)." (PMID 32231867, 2020). "Released by tumor and myeloid derived suppressor cells, IDO1 depletes T-cells of tryptophan, thereby attenuating their activity." (PMID 33065994, 2020). "In the phase III clinical trial of epacadostat, IDO1 gene expression in tumor samples was quantified by in situ hybridization." (PMID 33584686, 2020). "Other studies established that the combination of immune checkpoint blockade and IDO1 pathway inhibition results in potent reactivation of tumor infiltrating T cells and/or tumor-resident immunosuppressive regulatory T cells." (PMID 33085694, 2020). "A reduction in systemic Kyn levels is only an indirect readout, given that the IDO1 inhibitors are targeting the tumour microenvironment." (PMID 31819194, 2020). "IFN-γ is involved in anti-viral and anti-tumor immune responses by triggering transcription of several genes such as Ido-1 which is transcriptionally regulated by IFN-γ through activation of Jak-1 and STAT-1 but also NF-κB." (PMID 32384638, 2020). "Gene set enrichment analysis revealed that agonistic CD40 mAb therapy increased interferon (IFN)-related responses in tumor endothelial cells, including up-regulation of the immunosuppressive enzyme Indoleamine 2, 3-Dioxygenase 1 (IDO1)." (PMID 32231867, 2020). "This is in contrast with the results obtained by Holmgaard and coworkers, who describe the first use of this model, and who describe an increased tumor growth rate after IDO1 overexpression, which is reduced by IDO1 inhibitor treatment." (PMID 33584686, 2020). "We found that agonistic CD40 mAb treatment increased immunosuppression in tumor endothelial cells characterized by up-regulation of IDO1." (PMID 32231867, 2020). "The notion of inhibiting IDO1 using small-molecule inhibitors elicited high hopes of a positive impact in the field of immuno-oncology, by restoring anti-tumour immune responses and synergising with other immunotherapies such as immune checkpoint inhibition." (PMID 31819194, 2020). "IDO1 recruits tumor-infiltrating MDSCs into tumor milieu and is responsible for MDSC-associated activation and/or recruitment of Tregs in cancer." (PMID 30777103, 2019). "Indoleamine 2,3-dioxygenase 1 (IDO1) is a catabolizing enzyme that induces immune tolerance by suppressing T cells through tryptophan depletion and kynurenine accumulation in the local tumor microenvironment." (PMID 31671550, 2019). "Indoleamine 2,3-dioxygenase 1 (IDO1) is an enzyme that participates in tumor immune escape primarily by catalyzing tryptophan to l-kynurenine." (PMID 31324754, 2019). "Membrane PD-L2 expression and cytoplasmic IDO1 expression were defined by tumor proportion score (TPS); samples with TPS < 1% were considered negative." (PMID 31163080, 2019). "There are preclinical evidences that IDO1 inhibition can disrupt acquired immune tolerance, enhance tumor-specific killing, and significantly increase the immune response induced by various chemotherapeutic and immunotherapeutic agents." (PMID 32047753, 2019). "Similar to human basal-like BC, BBN-induced murine tumors displayed an upregulated expression of immunoinhibitory molecules such as CTLA-4, PD-L1, and IDO1 which can lead to cytotoxic resistance and tumor escape." (PMID 31779626, 2019). "1-MT, the inhibitor of immunosuppressive molecule IDO1, partially reduced the tumor-promoting activity of IFN-γ-primed AFMSCs." (PMID 31149015, 2019). "In our study, the expression level of IDO1 was up-regulated after tumour-bearing DCs co-cultured with cryo-thermal-activated eosinophils as compared to tumour-bearing DCs co-cultured with tumour-bearing eosinophils." (PMID 31519961, 2019).
tumor (continued). "IDO1 contributes to tumor progression in vivo by suppressing tumor-infiltrating T lymphocytes and NK cells and activating regulatory T cells." (PMID 31391111, 2019). "The combination of IDO1 shRNA and the Her2/neu DNA vaccine has induced a better anti-tumor effect than the Her2/neu DNA vaccine alone, in an endogenous Her2/neu-overexpressing bladder tumor model." (PMID 30658461, 2019). "Various preclinical studies with cancer models suggest that overexpression of IDO1 enzyme induces tumor progression and metastasis." (PMID 31804586, 2019). "Knockdown of IDO1 expression reduced tumor cell growth, colony formation, migration, and invasion, but induced tumor cell apoptosis." (PMID 31355138, 2019). "IDO1 was a credible target of miR-448 which, as a tumor-suppressive miRNA, enhances the CD8+ T cell response by inhibiting IDO1 expression." (PMID 31391111, 2019). "IDO1 is mainly expressed in the intracellular of tumor cell, we tried to measure the concentration of IDO1 in the culture supernatant by ELISA." (PMID 31391111, 2019). "We found a significant increase of IDO1 in metastasis VS primary PCa (p = 0.014) and a similar upregulation was detected in tumor and tumor adjacent tissues compared to normal tissue." (PMID 31842810, 2019). "Our group has demonstrated TGF-β to promote IDO1 expression in plasmacytoid DCs, thus facilitating local Treg differentiation within the tumor microenvironment." (PMID 31921140, 2019). "Intramuscular injection of IDO1 shRNA also delayed tumor growth in a subcutaneous murine lung tumor model and increased CD11b+Ly6G+ neutrophils infiltration into the tumor." (PMID 30658461, 2019). "The monoclonal antibodies bind to programmed cell death protein-1 (PD-1), cytotoxic T-lymphocyte-associated antigen-4 (CTLA4), and indoleamine-2,3-dioxygenase 1 (IDO1), thereby, relieving T-cells from immunosuppression by tumor cells." (PMID 31075138, 2019). "Significantly higher mRNA expression of IDO1 was observed in tumor samples than in normal skin samples (P < 0.01)." (PMID 30682105, 2019). "Indoleamine 2,3-dioxygenase 1 (IDO1), a tryptophan catabolising enzyme, is known as a tumour cell survival factor that causes immune escape in several types of cancer." (PMID 31423846, 2019). "We compared the mRNA transcription level of IDO1 in tumor samples from EMPD patients and normal skin samples." (PMID 30682105, 2019). "These IDO1 expressing DCs induce tumor specific iTreg capable of suppressing tumor protein specific CD8+ T cell activity." (PMID 31681327, 2019). "The silencing of IDO1 in DC by the YSK12-MEND significantly enhanced the antitumor effect against E.G7-OVA tumor." (PMID 31383907, 2019). "In normal conditions, IDO1 controls excessive immune activation preventing autoimmunity, however, tumor cells upregulate IDO1 activity by depleting tryptophan in the tumor microenvironment." (PMID 31337018, 2019). "IDO1 induces the expression of pro-tumoral cytokines such as IL-6, which recruits MDSCs at the tumor site." (PMID 30708988, 2019). "Our results also showed that low IDO1 and CD47 in tumour cells associated with improved prognosis, further supporting the importance of TAMs." (PMID 31358801, 2019). "As expected, tumor tissues expressed significantly higher levels of IDO1 than normal mucosa (P < 0.001)." (PMID 30717285, 2019). "Over-expression and over-activation of IDO1 in tumors and antigen-presenting cells play important roles in tumor-induced tolerance and suppression of the immune system by depleting the essential amino acid tryptophan and producing toxic tryptophan metabolites." (PMID 30777103, 2019). "Similar to IDO1, the PD-L1 mRNA expression levels were also notably higher in tumor tissues than in normal epithelium (P = 0.005)." (PMID 30717285, 2019). "Similar to CD47, tumour intensity of IDO1, a broadly studied immunosuppressive molecule, was used to group the samples into two categories." (PMID 31358801, 2019).
tumor (continued). "In some tumors, IDO1-expressing tumor cells are in lymphocyte-rich areas, meaning that IDO-expression can be the consequence of IFN-γ expression and a resistance mechanism." (PMID 30708988, 2019). "In that study, tumor grade, vascular invasion, and PD-L1 expression were independent predictors of IDO1 expression, but these were all pathological findings rather than clinical features." (PMID 31163080, 2019). "CAI strongly induced mRNA and protein expression of a key Try-metabolizing enzyme, IDO1, in both CTLs and B16 tumor tissues." (PMID 31511064, 2019). "In mouse models, decreased gene expression of IDO1 by shRNAs leads to the inhibition of tumor growth." (PMID 30708988, 2019). "During the development of anti-tumor drugs, potent IDO1 inhibitors were discovered, and intensive efforts have been made to develop potent IDO1/TDO inhibitors with various structural scaffolds." (PMID 31195673, 2019). "IFN-γ has also been reported to upregulate immunosuppressive molecules such as PD-L1 and IDO1, thus promoting tumor immune escape." (PMID 31511064, 2019). "The compound 1-methyl-d,l-tryptophan (1MT) is an inhibitor of IDO1, and single-agent administration of 1MT has delayed tumor outgrowth in a transgenic model of human epidermal growth factor receptor 2 (HER2)-driven breast cancer." (PMID 30658461, 2019). "Our data also show that among the 11 tested tumor cell lines, only five constitutively express IDO1." (PMID 31324754, 2019). "Further research showed that IFN-β mobilized the IDO1/Kyn/AhR/p27-dependent pathway to mediate tumor cells dormancy." (PMID 31297335, 2019). "In other cancers, IDO1 expression is constitutive and IDO1 expressing tumor cells are surrounded by less lymphocytes." (PMID 30708988, 2019). "It has been well known that tumor IDO1 promotes immunosuppression by direct action on effector T cells and Tregs, and through recruitment, expansion and activation of MDSCs." (PMID 30777103, 2019). "Given that IDO1 overexpression promoted tumor growth in tumor-bearing BALB/c mice in vivo, we used IHC techniques to further explore the potential mechanism by which stable IDO1 overexpression drives subcutaneous tumor growth in vivo." (PMID 31391111, 2019). "IDO1 overexpression in tumor cells also leads to reduced plasmatic amounts of tryptophan, meaning that the immunosuppressive effect of IDO1 is not locally restricted but is systemic." (PMID 30708988, 2019). "A phase I trial of tumor patients using Indoximod as an IDO1 inhibitor has shown that doses higher than 1,200 mg 1-MT in a patient do not increase peak serum levels over ~16 μM, indicating a limited accumulation of the applied inhibitor." (PMID 31417567, 2019). "In summary, these results suggested that the restriction of tumor growth by H2S was related to the downregulation of IDO1 expression and induction of CD8+ T cells and inhibition of MDSCs." (PMID 30777103, 2019). "We also performed a combined analysis of the CD47 and IDO1 tumour cell intensities using three-tiered classification; high intensity of both markers, high intensity of only one marker, low intensity of both markers." (PMID 31358801, 2019). "The expression of IDO1 was located in the cytoplasm and was mainly confined to tumor cells, while the expression of CD8 was located on the membrane of lymphocytes." (PMID 31391111, 2019). "Using H22 HCC-bearing mice, we found that H2S restricted tumor growth and exhibited immunotherapeutic efficacy by downregulating IDO1 expression, inducing T-effector cells, and inhibiting MDSCs." (PMID 30777103, 2019). "In summary, IDO1 inhibitor DX-03-12 exhibits promising drug like properties, good pharmacokinetic properties, low cellular toxicity, and impressive in vivo anti-tumor efficacy." (PMID 31195673, 2019). "We elucidated IDO1 function by performing cell-based assays and establishing transplanted tumor models in BALB/c mice and BALB/c nude mice." (PMID 31391111, 2019).
tumor (continued). "Other studies have confirmed that the tumor microenvironment has more inhibitory factors, including indoleamine 2,3-dioxygenase 1 (IDO1)." (PMID 31391111, 2019). "Similar to previous reports, the findings indicate that the use of siRNA for inhibition IDO1 activity in DCs represents an attractive strategy for reducing the levels of Treg cells in the tumor microenvironment." (PMID 31383907, 2019). "In tumor-draining lymph nodes, IDO1 expression of DCs is induced, and IDO1-expressing DCs suppress effector T cell proliferation and activate regulatory T cells because of tryptophan deprivation, downstream kynurenine, and other metabolites." (PMID 30658461, 2019). "In this study, we investigated the role of IDO1 in the tumor microenvironment by injecting CT26 cells with stable IDO1 overexpression into immune-competent mice." (PMID 31391111, 2019). "Like CSFR1, the rate-limiting, cytosolic enzyme indoleamine 2,3-dioxygenase-1 (IDO1) functions in the process of tumor-mediated immune evasion." (PMID 30654522, 2019). "Whereas, under pathophysiological conditions (e.g., in tumor cells) inflammatory signals up-regulate the expression of IDO1 enzyme." (PMID 31804586, 2019). "In cancers, it has been shown that an increased IDO1 activity promotes the development of an immunosuppressive microenvironment that can inhibit effective anti-tumor immune responses." (PMID 31417567, 2019). "High positive expression of PD-L1 and B7-H4 was observed in tumour cells (TCs), whereas PD-L1, B7-H3, B7-H4, IDO-1, VISTA, ICOS and OX40 were highly expressed in tumour-associated immune cells (TAICs)." (PMID 31722750, 2019). "For this reason, the IDO1 enzyme is known to perform as the sensor for tumor cells against T-cell attack." (PMID 31804586, 2019). "Meanwhile, the number of CD8+ T cells in tumor tissues of IDO1 overexpression group was significantly less than that in the vector control group." (PMID 31391111, 2019). "Actually, our data show that BET inhibitors inhibit tumor growth and simultaneously reduce the IDO1 expression in the xenografts." (PMID 31324754, 2019). "Consistently, pharmacological inhibition of IDO1 reverses the immune suppression in tumor microenvironments and improves the efficacy of therapeutic vaccination, chemotherapy or radiation therapy." (PMID 30777103, 2019). "In conclusion, compound DX-03-12 is a potent lead compound for developing IDO1 inhibitors and anti-tumor agents." (PMID 31195673, 2019). "The in vivo pharmacokinetic profile and anti-tumor efficacy of a potent IDO1 inhibitor were evaluated to explore its potential as an anti-tumor agent." (PMID 31195673, 2019). "Presence of IDO1 positive immune cells was highest in Group 3 tumors (90%; p = 0.217) and was associated with IP10 expression in the tumor (p = 0.017)." (PMID 31050820, 2019). "IDO1 has also been reported to be upregulated by both hypoxia and adenosine, which are typical components of the tumor microenvironment encountered by DCs." (PMID 31921140, 2019). "IDO1 was found to be broadly expressed in human tumors and thought to contribute to cancer development primarily by facilitating tumor immune escape." (PMID 30112109, 2018). "IDO1 has diverse biological roles in immune suppression and tumor progression, rendering it an attractive target in cancer therapeutic development." (PMID 30068361, 2018). "Another tolerant molecule is IDO1, a kynurenine pathway enzyme, which is expressed by tumor cells to evade a potential effective immune response." (PMID 30039553, 2018). "As the number of mechanisms and thus possible targets is steadily increasing, a key question arises – can modulation of one metabolic pathway, such as through IDO1 blockade, influence the outcome of immune-cancer interaction to induce tumor regression?" (PMID 30076128, 2018). "Upregulation of IDO1 by IFN-γ in tumor cells is believed to generate an immunosuppressive tumor microenvironment that restricts cytotoxic T cells." (PMID 29685162, 2018).